TWIST1 (twist family bHLH transcription factor 1)
Diseases named in the same sentence as TWIST1 in open-access papers (continued):
Sharing a sentence is not in itself a finding about the gene and the disease.
Obesity (19 papers, 2012 to 2024). Accumulation of substantial excess body fat. "The expression level of Twist1 in WAT is downregulated in obesity but can be restored after weight loss." (PMID 37996425, 2023). "Obesity is also associated with PH and cellular senescence is induced in an obese condition, in which angiogenesis is impaired through TWIST1 signaling." (PMID 36203755, 2022). "TWIST1 controls cellular metabolism and is involved in obesity- and angiogenesis-associated diseases." (PMID 34660572, 2021). "In this context, over-expression of Twist1 caused a reduction in mitochondria, while heterozygous Twist1 mice were obesity resistant on a high-fat diet due to an increase in expression of oxidation genes." (PMID 22815831, 2012). "Taken together, Twist1 is a novel transcription factor with profound implications in the development of obesity-associated WAT inflammation and insulin resistance, which provides a prospective mechanism linking Twist1 expression with the obesity-associated diseases." (PMID 37784111, 2023). "Twist1 has also been found to associate with insulin resistance (IR) in adipocytes, which may provide us a new therapeutic direction towards diabetes and obesity." (PMID 37784111, 2023). "TWIST1 is also involved in DNA methylation that is associated with obesity." (PMID 34660572, 2021). "While our results demonstrate that overexpression of TWIST1 in obese human adipose ECs restores vascular formation, which may restore adipose tissue homeostasis, it is reported that transgenic mice overexpressing Twist1 in the adipose tissue are susceptible to obesity." (PMID 34660572, 2021). "Although Twist1 has been found in skeletal muscle, the expression of Twist1 in the skeletal muscle is unchanged under the situation of obesity, T2D, and exercise training." (PMID 37784111, 2023). "Consistently, Twist1 was upregulated during 3T3-L1 preadipocyte differentiation without crippling lipid formation and was negatively correlated with the obesity development." (PMID 37784111, 2023). "TWIST1 also controls cellular metabolism; knockdown of TWIST1 in fat cells stimulates oxygen consumption and mitochondrial biogenesis, which results in resistance to obesity." (PMID 34660572, 2021). "To specifically examine the effects of obesity on TWIST1 expression in ECs, we isolated ECs from obese (BMI > 30) vs. lean (BMI < 30) human subcutaneous adipose tissues and measured the mRNA levels of TWIST1." (PMID 34660572, 2021). "Aberrant expression of nephroblastoma overexpressed (NOV) and Twist1 are evident in inflammation and obesity." (PMID 31906399, 2020). "Heterozygous knockout mice of Twist1 showed an obesity-resistant phenotype when placed on a high-fat diet and increased brown fat metabolism by elevated oxygen consumption, mitochondrial biogenesis, and uncoupling in BAT." (PMID 32340411, 2020). "Decreased expression of TWIST1 results in elevated secretion of TNFα, which is responsible for the progression of obesity and insulin resistance." (PMID 30678306, 2019). "A regulatory cascade involving PPARγ and TWIST1 was found in low-grade chronic inflammation in humans, which is a major characteristic of obesity and results from deregulated white adipose tissue function." (PMID 25128964, 2014). "Nonetheless, Twist1 gene expression is highly correlated with BMI and is reduced in obesity and increased following surgical or caloric restriction weight loss in both SAT and VAT in humans." (PMID 22969750, 2012). "In the following chapters the potential functional roles of Twist1 in AT and contributing mechanisms to the pathogenesis of obesity and insulin resistance will be discussed." (PMID 22969750, 2012). "Interestingly, the controversial discoveries were found in animal studies, suggesting that Twist1 transgenic mice were more prone to high-fat diet-induced obesity phenotype, whereas Twist1 heterozygous knockout mice displayed obesity-resistance phenotype." (PMID 37784111, 2023).
Obesity (continued). "In humans, Twist1 gene expression level is decreased in obesity and increased following surgical or caloric restriction weight loss in both subcutaneous adipose tissue (SAT) and visceral adipose tissue (VAT) despite of its differential expression in the SAT and VAT." (PMID 37784111, 2023). "In prospect, Twist1 might be a potential molecular therapy target and Twist1 agonist might be beneficial in controlling adipogenesis and harnessing obesity." (PMID 37996425, 2023). "Therefore, modulation of Twist1 by miR-337-3p represents a potential strategy to counteract obesity and its metabolic alterations." (PMID 32340411, 2020). "Interestingly, other studies reported the function of TWIST1 during white adipose tissue inflammation and its correlation with obesity and insulin resistance." (PMID 32798719, 2020). "However, additional studies in human brown adipocytes are critical to confirm this mechanism described in rodents and to establish the potential contribution of Twist1 to regulation of energy expenditure and obesity in humans." (PMID 22969750, 2012). "Therefore, the direct role of Twist1 in matrix remodeling that accompanies AT expansion in obesity is conceivable and is worth future investigation." (PMID 22969750, 2012). "Since a decrease of energy expenditure was proposed to contribute to white fat accumulation and obesity this study suggests that Twist1 may be a positive indirect contributor to fat accumulation leading to obesity." (PMID 22969750, 2012). "Thus, Twist1 may function as an anti-obesity factor during adipogenesis and this function is likely via the interaction between Twist1 and PPARγ." (PMID 37996425, 2023). "Moreover, the Twist1 expression in human WAT was relatively low under the circumstances of obesity and insulin-resistance, which may be mediated by an increased sensitivity to the proinflammatory effect of TNF-α." (PMID 37784111, 2023). "Therefore, targeting Twist1 by miRNA intervention could become a strategy for the treatment of obesity and metabolic disease." (PMID 32340411, 2020). "Further silencing experiments are needed to clarify the role of TWIST-1 as a key regulator of balance in ECM remodeling and a possible anti-obesity target." (PMID 37569456, 2023). "Obesity contributes to the inhibition of TWIST1-SLIT2 signaling and impaired angiogenesis, while Twist1 acts as a mechanosensor that senses ECM stiffness." (PMID 36496995, 2022). "Therefore, targeting Twist1 could become a strategy for obesity and metabolic disease." (PMID 32340411, 2020). "It seems that the effect of obesity and MetS in VAT is higher than the one produced by the effect by miR-337-3p increased, and Twist1 decreased." (PMID 32340411, 2020). "Furthermore, BC-specific mortality was higher in patients with obesity and WBCs with low LUMA levels and hypermethylation of the adenomatous polyposis coli (APC) and twist family bHLH transcription factor 1 (TWIST1) genes." (PMID 37512149, 2023). "Twist1 mRNA expression was also 2.2-times higher in ECs isolated from Lepob/+ mouse lungs 7 days after PNX, while the levels of Twist1 did not significantly change in post-PNX Lepob/ob mouse lung ECs, suggesting that obesity inhibits post-PNX induction of Twist1 expression." (PMID 39479393, 2024).
squamous cell carcinoma (18 papers, 2012 to 2025). A carcinoma arising from squamous epithelial cells. "Overexpression of TWIST1 is involved in the dissemination of squamous cell cancer; however, once the cells reach the metastatic site, downregulation of TWIST1 facilitates the colonization of metastatic cancer cells." (PMID 41321380, 2025). "We detected P-STAT3, ZEB1, and Twist1 in squamous cell carcinoma tissues and adjacent tissues by immunohistochemistry." (PMID 33363013, 2020). "Twist1 induction in a squamous cell carcinoma mouse tumor model dramatically increases the number of CTCs compared with control mice, and these CTCs have an EMT phenotype, indicating that activation of EMT directly promotes the production of CTCs." (PMID 29416649, 2018). "Autophagy deficiency was found to increase SQSTM1/p62 levels, resulting in reduced E-cadherin expression, stabilization of the oncogenic protein Twist1 and promotion of cell migration, invasion and proliferation of human squamous cell carcinomas." (PMID 28109268, 2017). "TWIST1 was similarly overexpressed in all the histologies examined including adenocarcinoma and squamous cell carcinoma (p<0.0001 by ANOVA)." (PMID 22654667, 2012). "In contrast, MMTV-Cre;K-rasG12D;Twist1 mice invariably developed aggressive multifocal squamous cell carcinomas (SCC) at very young ages necessitating euthanasia at the significantly earlier median age of 35 days (n = 12, p<0.0001)." (PMID 22654675, 2012). "Two models targeted Snai1 and Twist1 to control EMT in breast and squamous carcinoma models, respectively." (PMID 34768901, 2021). "Likewise, TWIST1 was also reported to promote proliferation of early metastatic colonies, but not primary tumor in squamous cell carcinoma." (PMID 35152264, 2022).
thyroid cancer (18 papers, 2014 to 2024). "This evidence is corroborated in earlier studies showing higher Twist1 protein levels in ATC compared with normal thyroid and DTC and the ability of the Twist1/miR-584/TUSC2 pathway to induce resistance to apoptosis in thyroid cancer cells." (PMID 38256193, 2024). "This assumption is further corroborated by the reported ability of the Twist1/miR-584/TUSC2 pathway to induce a resistance to apoptosis of thyroid cancer cells." (PMID 34575184, 2021). "All told, these findings appear to suggest a prominent role of Twist1 in the formation of more aggressive thyroid cancers." (PMID 34575184, 2021). "The Twist1/miR-584/TUSC2 pathway plays a role in the resistance to apoptosis in thyroid cancer cells." (PMID 33381597, 2020). "In thyroid carcinoma, LEPREL1 has been found to serve as a target of the TWIST1 transcription factor (associated with epithelial-to-mesenchymal transition, metastasis formation and a poor prognosis)." (PMID 29956121, 2018). "TWIST proteins are over-expressed in a significant fraction of thyroid cancers and knockdown of TWIST1 in thyroid cancer cell lines led to a reduction in proliferation and migration." (PMID 28350298, 2017). "In conclusion, our study identified a novel TWIST1/miR-584/TUSC2 pathway that plays a role in resistance to apoptosis of thyroid cancer cells." (PMID 27661106, 2016). "Here, using a miRNome screening analysis of papillary thyroid cancer cells (TPC-1, hereafter named TPC) ectopically expressing TWIST1 compared to control cells, we found that miR-584 was up-regulated by TWIST1, and we studied its role in thyroid cancer cells." (PMID 27661106, 2016). "Recently, we identified a set of mRNAs that mediates the biological effects of TWIST1 in thyroid cancer cells." (PMID 27661106, 2016). "In synovial sarcoma cells, Twist1 direct downstream targets are involved in maintenance of mesenchymal differentiation, and Twist1 targets promote cell migration and proliferation in thyroid cancer cells." (PMID 25262113, 2014). "In addition, it has been demonstrated that the most upregulated genes induced by Twist1 in thyroid cancer cells are those controlling motility, proliferation, cell death, and survival." (PMID 38256193, 2024). "In addition, TWIST1 increased (about 2-fold) the ability of thyroid cancer cells to migrate into collagen I matrix, whereas TWIST1 knockdown in CAL62 cells reduced cell migration into collagen I matrix." (PMID 35242497, 2022). "Further study found that the decreased expression of E-cadherin protein in thyroid cancer cell lines stimulated by inflammatory factors may be related to the activation of transcription factors Snail, Slug, Twist1 and Zeb1." (PMID 34930256, 2021). "By immunohistochemistry several transcription factors implicated in EMT induction, such as SLUG (SNAI2), TWIST1 and ZEB1 are all up-regulated in ATC compared to normal thyroid and well-differentiated thyroid cancers and coordinately act to repress E-cadherin (CDH1) expression." (PMID 29383121, 2017). "TWIST1 sustains the invasive and migratory phenotype of thyroid cancer cells; therefore, we investigated whether miR-584 was in part responsible for these effects." (PMID 27661106, 2016). "Here, we identified a set of potential miRNAs targets of Twist1 in thyroid cancer cells." (PMID 27661106, 2016). "In thyroid cancer, ETV5 promoted the mesenchymal morphology of cancer cells by regulating the mRNA levels of twist family BHLH transcription factors 1 (TWIST1) and snail family transcriptional repressors 1 (SNAI1)." (PMID 36872348, 2023). "This is particularly true for the RAC1/PAK1 pathway, TWIST1 and EGFR1 proteins, which are known drivers of proliferation and EMT in aggressive thyroid cancer cells." (PMID 34638434, 2021). "Anaplastic thyroid carcinoma (ATC) is one of the deadliest human malignancies; TWIST1 is overexpressed in ATC and increases thyroid cancer cell survival, migration and invasion." (PMID 27661106, 2016).
thyroid cancer (continued). "Importantly, some classical oncogenes, such as PIK3CA, TWIST1, HER2, and HER3 were identified as the direct targets of ETS factors in thyroid cancer." (PMID 34221969, 2021). "Although, from the multivariate analysis, its prognostic value did not emerge, Twist1 might represent a valuable therapeutic target, warranting further investigation for the treatment of more aggressive thyroid cancers." (PMID 34575184, 2021). "In addition, knockdown of TWIST1 using siRNA in ATC cell lines induced apoptosis and inhibited cell migration and invasion; alternatively, overexpression of TWIST1 by transfection into thyroid carcinoma cell lines induced resistance to apoptosis and increased cell migration and invasion." (PMID 29383121, 2017).
esophageal squamous cell carcinoma (17 papers, 2011 to 2026). Esophageal squamous cell carcinoma (ESCC) is a type of esophageal carcinoma (EC) that can affect any part of the esophagus, but is usually located in the upper or middle third. "Studies have shown that patients with esophageal squamous cell carcinoma overexpressing TWIST1 had a poor prognosis, and the increase of TWIST1 can affected the invasion and migration ability of esophageal squamous cell carcinoma." (PMID 35799142, 2022). "It had been already shown that Twist1 induces EMT in esophageal squamous cell carcinoma (ESCC) cell lines by up-regulating several genes." (PMID 25629807, 2015). "Our aim in this study was to investigate the functional correlation between TWIST1 and the involved genes in the process of CSCs self-renewal in human esophageal squamous cell carcinoma (ESCC) line KYSE-30." (PMID 36553636, 2022). "Our aim here is to elucidate impact of ectopic expression of TWIST1 on OCT4 gene expression in esophageal squamous cell carcinoma (ESCC)." (PMID 29299035, 2017). "In esophageal squamous cell carcinoma, IHC has shown co-expression of ADAMTS6 and Twist1 in patient tumors." (PMID 41465277, 2025). "In esophageal squamous cell carcinoma (ESCC) cell lines, TWIST1 is a crucial transcription factor that enhances the epithelial-mesenchymal transition (EMT) by downregulating E-cadherin and upregulating mesenchymal genes such as N-cadherin, ZEB2, vimentin, and fibronectin." (PMID 38589525, 2024).
neuroblastoma (16 papers, 2006 to 2025). Neuroblastoma (NB) is the most common solid, extracranial childhood tumor. "Quantitative transcriptional profiling showed an increase in the expression of 29 molecules, including BMPs, Notch2, Slug, and Twist1, associated with the stem state in cancer stem cells of neuroblastoma." (PMID 30116755, 2018). "Hence, it can be hypothesized that the transcriptional axis MYCN/TWIST1/DDR2/SNAIL1 could drive high-risk neuroblastoma tumor invasion and metastasis." (PMID 34716856, 2022). "In neuroblastoma, TWIST1 co-occupies enhancers with MYCN and is required for MYCN–dependent proliferation." (PMID 40962798, 2025). "In further analyses on the R2 Genomics Platform, we found very significant correlations between DDR2 and TWIST1 expression in every single neuroblastoma patient dataset available." (PMID 34716856, 2022). "The four UHR-NB upregulated genes (ADAM22, GAL, KLHL13 and TWIST1) were all upregulated in MYCN amplified neuroblastoma in 5 additional cohorts." (PMID 32629858, 2020). "As our data demonstrates that Twist1 can functionally antagonize key regulators of a sympathetic neuronal identity, it would be of interest to closely examine the function of TWIST1 in neuroblastomas and other tumors affecting neuronal derivatives of NCCs." (PMID 23555309, 2013). "Fzd6 positive neuroblastoma cells form neurospheres with high efficiency, are resistant to doxorubicin killing and express high levels of mesenchymal markers such as Twist1 and Notch1." (PMID 22249030, 2011). "It is worth noting that in neuroblastoma, TWIST1 is a direct transcriptional target of MYC/MYCN." (PMID 34716856, 2022). "Moreover, overexpression of TWIST1 in neuroblastoma cells resulted in increased DNM3OS levels, and luciferase reporter assays showed that the TWIST1-binding domain in the promoter of the DNM3OS locus was necessary for expression." (PMID 29150601, 2017). "Functional studies revealed that TWIST1 promotes both primary and metastatic neuroblastoma (NB) tumor growth." (PMID 35022561, 2022). "Importantly, diminished levels of ZEB, TWIST1, and SNAIL were detected in neuroblastoma xenografts from mice treated with GSK595 compared to controls." (PMID 35803962, 2022). "We identified 88 transcription factors, many of which have been described previously as part of the core regulatory transcription factor circuitry in specific cancer types, such as PHOX2B, TWIST1, and ISL1 in neuroblastoma; MYOD1 and MYOG in rhabdomyosarcoma; NR0B1 in Ewing sarcoma." (PMID 34818552, 2021).
sarcoma (15 papers, 2012 to 2023). A usually aggressive malignant neoplasm of the soft tissue or bone. "TWIST1 has been implicated in tumor initiation, stemness, angiogenesis, dissemination, and chemoresistance in various carcinomas, sarcomas, and hematological malignancies." (PMID 30154425, 2019). "TWIST1, as a regulator of EMT in embryogenesis, is involved in the tumorigenesis of different cancers, including sarcomas, carcinomas, and hematological malignancies." (PMID 36553636, 2022). "In sarcomas, signaling pathways including the MAPK/ERK, Wnt/β-catenin, TGF-β and PI3K/Akt, EMT transcription factors ZEB1/2, SLUG, SNAIL, and TWIST1 promote migration, invasion, and metastasis." (PMID 35145908, 2021). "TWIST1, a basic helix-loop-helix (bHLH) transcription factor, was originally identified as a mesoderm-inducing factor in Drosophila and is known as a major inducer of EMT in human mammary epithelial cells and other cancers such as sarcoma, melanoma, and lymphoma." (PMID 30154425, 2019).